ADAMTS2 (ADAM metallopeptidase with thrombospondin type 1 motif 2)
Diseases named in the same sentence as ADAMTS2 in open-access papers (continued):
Sharing a sentence is not in itself a finding about the gene and the disease.
tumor (19 papers, 2012 to 2026). "Compared with the normal tissues, ADAMTS2 expression in GC tumor cells and fibroblasts was significantly increased, and the up-regulation of the ADAMTS2 was associated with poor prognosis of GC patients." (PMID 33851708, 2021). "ADAMTS-2 reduces endothelial cell proliferation and has angiogenic and anti-tumor molecular functions." (PMID 35883515, 2022). "It has been proposed that ADAMTS2 exerts an anti-tumor effect by inhibiting intratumoral vascularization." (PMID 36627894, 2022). "Particularly for P4, the shared mutations included several important tumor metastasis–related and drug-resistance genes, such as ZNF143, MUC16, NUMA1, ADAMTS2, and MOV10." (PMID 34616428, 2021). "Expression of HLAB, protein 14-3-3β, LTBP3, ADAMTS2, JAG2 and NME2 on tumour cells was significantly associated with clinical parameters related to tumour progression, invasion and metastasis." (PMID 30679934, 2019). "We found that the expression of ADAMTS2 was down-regulated in the tumour cells of patients that metastasized compared to those that did not metastasize." (PMID 30679934, 2019). "Proteins, HLAB, ADAMTS2, LTBP3, JAG2 and NME2 were significantly associated with tumor progression, vascular invasion and distant liver metastasis." (PMID 30679934, 2019). "Six of the 10 (60%) proteins examined using TMA immunohistochemistry, HLAB, protein 14-3-3β, LTBP3, ADAMTS2, JAG2 and NME2, were significantly associated with clinical parameters which have shown to relate with tumor progression, invasion and metastasis." (PMID 30679934, 2019). "Functionally, ADAMTS2 promoted PCa cell aggressiveness in vitro and tumor growth in vivo." (PMID 42125710, 2026). "siRNA-mediated knockdown of ADAMTS2 in specific tumor cell lines or in situ in specific animal models may also aid in the evaluation of its role in specific tumor progression." (PMID 40837410, 2025). "It is, however, important to note that several of the referenced articles use transcriptomic data extracted from total tumor tissues, and thus, ADAMTS2 expression may correlate with desmoplastic reactions." (PMID 40837410, 2025). "Since the metastatic activity of LOX is strongly linked to its enzyme activity and fibrosis, one could propose that high levels of ADAMTS2 or 14 would act as fibrosis inhibitors or tumor suppressors." (PMID 35563478, 2022). "In addition, ADAMTS2-overexpressing HEK293-EBNA cells drastically reduced tumor growth when grafted subcutaneously into nude mice." (PMID 24213506, 2012). "- Suppressed tumor angiogenesis in ADAMTS2 overexpressing tumors." (PMID 24213506, 2012). "Thus, ADAMTS2 is an example of a family member which suppresses tumor growth through inhibiting angiogenesis." (PMID 24213506, 2012). "This potential role of ADAMTS2, -3, and -14 may be of importance in conditions where abnormal lymphangiogenesis is part of the pathology (e.g., tumor aggressiveness), as a blockade of these enzymes could then be a potential therapeutic strategy in these conditions." (PMID 40837410, 2025). "ADAMTS-2 is associated with tumor progression and invasion, metastasis and CRC-specific survival, and may serve as a potential biomarker to stratify CRC patients into low and high risk of tumor metastasis." (PMID 36185995, 2022). "Expression of HLAB, ADAMTS2, LTBP3, JAG2 and NME2 on tumour cells, was associated with tumour progression and invasion, metastasis and CRC specific survival may serve as potential biomarkers to stratify CRC patients into low and high risk of tumour metastasis." (PMID 30679934, 2019). "In contrast, eight genes (COL1A1, COL5A1, COL1A2, COL3A1, WNT2, C1QTNF3, ADAMTS2, GXYLT2) exhibited elevated expression in tumor compared to normal tissue." (PMID 39062832, 2024). "KEGG analysis indicated that ADAMTS2, COL12A1, and THBS2 are closely related to ECM, and ECM plays an important role in tumor metastasis and progression." (PMID 35879877, 2023).
tumor (continued). "One possibility is that the 25 kDa enzyme generated after ADAMTS2/14 cleavage would have increased substrate specificity for a tumor promoting target rather than collagen, such as PDGFRβ, increasing PDGF signaling and cancer progression." (PMID 35563478, 2022). "ADAMTS-2, ADAMTS-3, and ADAMTS-14, collectively forming the procollagen N-protease, participate in several physiological processes in vivo, including blood coagulation, growth and evolution, signal transduction, and tumor progression." (PMID 35883515, 2022).
connective tissue disorder (7 papers, 2013 to 2020). A disease involving the connective tissue. "In vitro, ADAMTS-2, -3 and -14 have been shown to participate in processing of fibrillar procollagen types I–III, and ADAMTS-2 mutations have been linked to Ehlers–Danlos syndrome, a connective tissue disorder characterized by impaired collagen assembly." (PMID 29393911, 2018). "Mutation in ADAMTS2 causes the connective tissue disease Ehlers–Danlos syndrome." (PMID 27535281, 2016). "Mutations in the ADAMTS2 gene can induce the Ehlers-Danlos syndrome type VIIC, a recessive inherited connective-tissue disorder." (PMID 25515027, 2014). "Other networks significantly enriched also related to a further network in connective tissue disorders that contained genes including collagens COL10A1, COL11A1 and COL2A1 plus a disintegrin and metalloproteinase with thrombospondin motifs-2 (ADAMTS-2) and fibulin-1 (FBLN1)." (PMID 23971731, 2013).
cardiovascular disease (4 papers, 2022 to 2025). "We identified two loci at 5q35 (ADAMTS2) and 5q23 (PRR16), not previously reported for T2D using CC-GWAS and Fam-meta; both genes play a role in cardiovascular diseases." (PMID 36182916, 2022).
brain diseases (1 paper, 2022). "The association between ADAMTS2 and reelin could explain ADAMTS2’s association with multiple brain diseases but further mechanistic studies are clearly required." (PMID 35557837, 2022).
ADAMTS2 also shares sentences with these, for which no sentence is quoted: breast carcinoma (4 papers); COVID-19 (4); acute leukemia (2); osteoarthritis (2); acute respiratory distress syndrome (1); arthrochalasia EDS (1); Ataxia (1); Autoimmunity (1); bleeding disorders (1); blood disorders (1); chronic pancreatitis (1); cornea plana (1); corneal dystrophies (1); depression (1); diabetes (1); dysautonomia (1); emphysema (1); episodic ataxia (1); Ewing sarcoma (1); gastric tumor (1); glomerulonephritis (1); Hernia (1); hyperopia (1); infertile (1); Inguinal hernia (1); Kyphoscoliosis (1); Loeys-Dietz syndrome (1); Lymphadenopathy (1); neurodegenerative disease (1); Obesity (1).
A further 10 diseases each share a sentence with ADAMTS2 in 1 paper.